INS (insulin)
Diseases named in the same sentence as INS in open-access papers (continued):
Sharing a sentence is not in itself a finding about the gene and the disease.
cancer (continued). "Endogenic glucose is not only consumed by cancer and brain cells but also can serve as a signal to the glucose β-cell sensor stimulating insulin secretion." (PMID 32426290, 2020). "The human small RNA miR-4443 is functionally involved in several types of cancer and in the biology of the immune system, downstream of insulin and leptin signaling." (PMID 32069948, 2020). "This is because the metabolism of cancer patients is altered, with higher proteolysis and lipolysis, increased hepatic production, reduced insulin sensitivity, and, therefore, increased energy expenditure." (PMID 33383949, 2020). "Vitamin D can regulate immune function, hematopoietic system, cancer development and progression, glucose homeostasis through insulin production and insulin resistance and cognitive function." (PMID 32518650, 2020). "Citrate acts as a regulator of multiple physiological and pathophysiological processes such as insulin secretion, inflammation, neurological disorders, and cancer." (PMID 33282912, 2020). "Insulin activates key cancer processes including EMT, tissue inflammation, motility, and angiogenesis." (PMID 32153503, 2020). "At the time of cancer diagnosis, 61% of patients with DM were using oral agents as diabetic therapy, 15% were using oral agents with insulin and 7% were using insulin alone." (PMID 33552546, 2020). "Several studies have demonstrated that during tumor progression, the influence of the insulin/IGF system on cancer cell behavior is primarily through the regulation of the epithelial-mesenchymal transition (EMT) program to obtain a malignant phenotype." (PMID 32500027, 2020). "One possible explanation for this observation is that metformin and insulin are thought to reduce the activity of mTOR, which blocks progression of the cell cycle and cancer growth." (PMID 32539807, 2020). "Strict insulin inhibition can result in two principle effects, both of which have the potential to induce cancer cell programmed cell death and to reduce proliferation of cancer cells." (PMID 33270630, 2020). "AMPK has been well recognized as an important integrator in a wide range of biological activities of adiponectin, including lipid metabolism, insulin sensitization, and control of growth and apoptosis in cancer cells." (PMID 32155890, 2020). "Insulin is known as an enhancer of cancer cell proliferation, inhibiting apoptosis by its receptor and insulin-like growth factor through the PI3K/Akt and MAPK pathways." (PMID 35582045, 2020). "The finding that cancer-secreted IGF-II can activate different targets compared to those activated by insulin through activation of the insulin receptor isoform A opens-up a novel scenario for the role of this ligand/receptor axis." (PMID 33266015, 2020). "Reductions in abdominal and visceral adiposity improve insulin sensitivity, lipid profile and cytokines, which consequently reduce the risk of CVD and some cancers." (PMID 33261185, 2020). "MCF7 exclusively targeted pathways related to proliferation and EMT/MET, such as axon guidance and focal adhesion together with cancer metabolic processes (insulin signaling pathways)." (PMID 33374139, 2020). "The previous review is focused on putative effects and mechanisms showing how tumor-host metabolic interactions form the “vicious cycle” (blue) which supports tumor growth via redirecting unutilized glucose from insulin-resistant host tissues to cancer cells." (PMID 32426290, 2020). "Mothers who experience starvation have high blood insulin concentrations and are also reported to have babies with poor health who have a high chance of developing diseases, including cancer." (PMID 32857726, 2020). "These include insulin sensitization, anti-inflammation, cardiovascular protection, anti-aging, anti-cancer and even anti-microbial effects." (PMID 33664665, 2020).
cancer (continued). "LRP5 is highly expressed in many tissues and is involved in the modulation of glucose-induced insulin secretion, bone development, and cholesterol metabolism, as well as cancer progression." (PMID 31031810, 2019). "For example, the insulin signalling pathway consisting of insulin growth factor receptors (IGFRs) are important mediators of cancer." (PMID 30845775, 2019). "There is also evidence suggesting that increased height is associated with increased risk of cancer and among mechanisms linking height with CAD and cancer are insulin and insulin-like growth factor signalling pathways." (PMID 30937401, 2019). "For example, insulin, an important regulator for carbohydrate and lipid metabolism and a growth factor for cell proliferation, can keep cancer stemness and EMT of CSCs in hepatocellular carcinoma and breast cancer." (PMID 30770752, 2019). "Increased tissue availability of circulating insulin/IGF1 and upregulation of insulin/IGF receptor signaling pathways has been implicated in the formation of different cancers in observational studies." (PMID 31139216, 2019). "Akt and its downstream effectors, including NF-κB, CREB, and mTOR, function in diverse cellular processes, including cancer progression and insulin metabolism." (PMID 31409352, 2019). "Inflammatory cytokines are signals from cancer tissues to induce catabolic responses in insulin-controlled adipose and muscle cells that potentiate their lipolysis, proteolysis, and IR." (PMID 31019893, 2019). "This also suggests that high-levels of both insulin and EGF in tumour microenvironment can be a risk factor for cancer escape." (PMID 30770752, 2019). "Accordingly, recent studies have shown that nutrient availability from the environment/host, dietary regimens, and hormonal status can affect host insulin homeostasis and cancer cell metabolism to enhance drug efficacy." (PMID 31319822, 2019). "Pathway enrichment anlysis results showed that the target genes enriched significantly in pathways related to cancer progression, such as ErbB, Insulin and MAPK signaling pathways." (PMID 31009516, 2019). "Oestradiol modulates cell cycle and apoptotic processes in insulin-primed cells, which then further promotes cancer cell growth." (PMID 31360518, 2019). "Emerging evidence indicates that in addition to regulating insulin signaling, cytoskeleton remodeling, and receptor endocytosis, SHIP2 is implicated in the development and progression of certain types of cancer." (PMID 30321069, 2019). "These insulin-dependent effects are consistent with the beneficial anti-cancer effects of metformin." (PMID 31360518, 2019). "Both PpIX and BPD inhibited the enzyme in Panc1 and MiaPaCa2 cancer cells as demonstrated by the Trx-dependent endpoint insulin reduction assay." (PMID 30820346, 2019). "Clusters of biological cells play an important role in normal and disease states, such as in the release of insulin from pancreatic islets and in the enhanced spread of cancer by clusters of circulating tumor cells." (PMID 31018537, 2019). "The ‘indirect’ anti-cancer effects of metformin arise from its ability to reduce insulin resistance, insulin levels, and fasting glucose levels." (PMID 31835318, 2019). "Insulin is an important regulator for cell metabolism and growth, it also plays a role in keeping cancer stemness and epithelial mesenchymal transition (EMT) of CSCs." (PMID 30770752, 2019). "Concordantly to the primary tumor derived RCC cells’ insulin rapidly increased migration rate of all metastatic cancer cell lines and embryonic kidney cell line." (PMID 30929166, 2019). "In cancer cells, serum from obese mice and humans, which have a number of altered metabolites including high levels of insulin, has been shown to increase cell migration in melanoma and PCa cells." (PMID 31379747, 2019).
cancer (continued). "Combining these observations with the gene expression data, we believe that insulin also has a stimulatory effect on SREBF1 transcription in cancer cells, in agreement with previous findings from liver studies." (PMID 30970006, 2019). "On the other hand, the top six pathways of down‐regulated circRNAs were proximal tubule bicarbonate reclamation, pancreatic secretion, vascular smooth muscle contraction, focal adhesion, insulin secretion and miRNAs in cancer." (PMID 31605569, 2019). "NGF stimulation of insulin pathway via IRS1 transactivation has been previously reported in cancer cells, and occurs upon IRS1 recruitment by the NGF receptor TrkA." (PMID 29736736, 2019). "We found that three pathways, “Pathways in cancer” (hsa05200), “Focal adhesion” (hsa04510), and “Insulin signaling pathway” (hsa04910), are widely affected by IQGAP1 and VAV2." (PMID 31798960, 2019). "IGF-1 pathways are activated by a high concentration of insulin, which then goes on to promote cancer development via the insulin/IGF-1 hybrid receptors." (PMID 31360518, 2019). "In this condition most of cancer cells consume glucose with a higher rate than insulin-controlled organs in the cancer-bearing host." (PMID 31019893, 2019). "In particular, cardioprotective insulin is thought to induce the development and progression of cancer, and anti-cancer drug resistance in cancer cells, which is harmful to patients with cancer." (PMID 31434946, 2019). "We identified that TCF7L2 rs290481, INS rs689, and INSR rs1799817 SNPs increased the susceptibility of AEG in different cancer stage subgroups." (PMID 31211453, 2019). "The increased potential of wound healing was significant in metastatic cell lines (p < 0.005 vs p < 0.05 for primary cancer site cell lines), which suggest that insulin conduct its stimulating signal through the IGF1R receptor in this case." (PMID 30929166, 2019). "Metabolic markers, such as insulin and IGFs, that have established links with clinical cancers are currently being employed as intermediate endpoints." (PMID 30809194, 2019). "With the current trend towards personalized cancer treatment, prospective studies are needed to better understand the exact mechanism by which metformin, statins, and insulin exert their effect on CRC survival." (PMID 31139216, 2019). "Metformin is currently being analyzed as a therapeutic alternative with insulin-dependent and insulin-independent mechanism of action against a several of cancer types." (PMID 31870092, 2019). "This not only indicates the selection advantage, and hence importance, of this pathway to many common human cancers but it also greatly confounds the interpretation of studies of the social regulation of this pathway by insulin/IGFs." (PMID 30809194, 2019). "Other pathways of interest included insulin signaling pathway (rno04910), axon guidance (rno04360), pathways in cancer (rno05200), purine metabolism (rno00230), glycerolipid metabolism (rno00561), and Fc gamma R-mediated phagocytosis (rno04666)." (PMID 31262088, 2019). "The relationship between insulin and cancer has been of interest among scientists and physicians for decades." (PMID 31719636, 2019). "The evidence linking metabolic disturbance (and insulin/IGFs) with cancer added to the shift toward considering prevention as a viable option." (PMID 30809194, 2019). "This opinion article describes how cancer cells metabolically reprogram the host cells by redirecting the majority of glycolytic fuel from the insulin-resistant host cells to glycolytic cancer cells." (PMID 31019893, 2019). "This is due to the relative insulin sensitivity of the epithelial cells that enhances insulin-mediated signalling that induces cancer cell proliferation and metastasis." (PMID 31831021, 2019).
cancer (continued). "In contrast, the KEGG enrichment pathways at 24 h poststimulus were axon guidance, insulin signaling pathway, and HTLV-I infection in MTcES+LPS and inositol phosphate metabolism, pathways in cancer, and insulin signaling pathway in MLPS." (PMID 31218234, 2019). "Pathways from KEGG were significantly enriched in insulin signaling activation, inositol metabolism, and cancer development." (PMID 31671785, 2019). "The decrease in blood glucose and insulin levels as a result of metformin administration reduced the proliferation of cancer cells and suppressed the growth of the tumor." (PMID 31835318, 2019). "In these tumors, the presence of HRs has important consequences for cancer responses to both insulin and IGFs." (PMID 30513575, 2018). "Pancreas is a complex tissue, and we should build on our knowledge on the impact of enhanced IGF-1R signaling on the “three-way”, insulin/IGF-driven interaction between cancer cells, endocrine pancreas, and the stroma." (PMID 29475434, 2018). "The abnormal IR transcript splicing causing an increased IR-A:IR-B ratio is a mechanism that potentiates the mitogenic response of cancer cells to circulating insulin and IGFs favoring tumor growth and progression." (PMID 30453495, 2018). "In cancer cells, the biological response to insulin cannot be predicted only on the basis of the IR and IGF-1R expression levels." (PMID 30453495, 2018). "In vitro studies indicate that in different cancer cell lines with different expression of the insulin and insulin-like receptors, insulin stimulates proliferation in all cell lines, but with different efficacy not necessarily related to the receptor content." (PMID 30453495, 2018). "Insulin/IGF-1R signaling is one of the signaling pathways that govern the sensitization of cancer cells to gemcitabine." (PMID 29475434, 2018). "Transient receptor potential melastatin member 4 (TRPM4), a non-selective cation channel, mediates cell membrane depolarization in immune response, insulin secretion, neurological disorders, and cancer." (PMID 29568272, 2018). "Activation of this pathway is a surrogate for mitogenicity of insulin analogues, which is important in view of concerns about long-term cancer risks of analogues with pro-proliferative activity." (PMID 29700562, 2018). "We re-validated the observed solo and synergistic effects of glucose and insulin on CA125 synthesis/secretion using in vitro cancer cell models (SKOV-3, HO8910, ES-2 and OVCAR-3)." (PMID 29716620, 2018). "Our animal and cancer cell models both revealed that, insulin, only when combined with a high-glucose condition can invoke the active release of CA125; otherwise, it promotes re-absorption of CA125." (PMID 29716620, 2018). "Tailored, targeted therapies against stromal insulin/IGF-1 signaling can have beneficial effects both on cancer progression and the deregulated endocrine function." (PMID 29475434, 2018). "The insulin/IGF/mTOR system has been shown to play a key role in CRC development due to its complex involvement in the cancer’s cellular metabolism, proliferation, and differentiation." (PMID 30257507, 2018). "PPARs not only serve critical roles in the control of lipid metabolism, but they are also implicated in the regulation of vascular diseases, cellular differentiation, insulin sensitization, and cancer." (PMID 30012954, 2018). "A growing body of evidence connects increased levels of blood glucose and insulin and chronic inflammation with cancer initiation and progression." (PMID 32984773, 2018). "Responsible for insulin signaling, Akt is known to induce resistance to apoptosis, changes in the cancer cells metabolism, reduction of beta-oxidation and increased synthesis of lipid in the cytosol." (PMID 29558948, 2018).
cancer (continued). "We, herein, demonstrated that overexpressed Mesothelin mediates 1.1- to 19.4-fold greater CA125 re-absorption in insulin-treated cancer cells compared with that in control cells, while Mesothelin overexpression itself is also modulated by the PI3K-Akt pathway." (PMID 29716620, 2018). "Insulin stimulates cell proliferation and most cancer cells express the insulin-like growth factor (IGF) receptor." (PMID 30213141, 2018). "The IR-A overexpression, and the increased IR-A:IR-B ratio, are mechanisms that promote the mitogenic response of cancer cells to insulin and IGF-2, which is produced locally by both epithelial and stromal cancer cells." (PMID 30453495, 2018). "Since metabolism both affects and is affected by transcriptional regulation, when errors do occur, metabolism at all scales is disrupted, from systemic insulin dysregulation in T2D to aerobic glycolysis in individual cancer cells." (PMID 29922517, 2018). "ME2 is a mitochondrial NAD(P)+ isoform, and because it affects two cofactors, it plays a key role in physiologic and pathologic functions, including insulin release, rapidly proliferating cancer cells, as well as epithelial-mesenchymal transition (EMT)." (PMID 30332737, 2018). "Aerobic exercise training can improve insulin sensitivity in many tissues; however, the relationship among exercise, insulin, and cancer cell growth is unclear." (PMID 29867528, 2018). "Beyond the classical role as a metabolic regulator, its role in inflammation, cancer, insulin secretion, histone acetylation, disorders and diseases has been highlighted." (PMID 30477251, 2018). "The modulation of cancer growth by metformin and of insulin sensitivity by anticancer drugs is so common that this phenomenon is being studied in hundreds of clinical trials on cancer." (PMID 30208162, 2018). "Transient receptor potential melastatin member 4 (TRPM4), a Ca2+-activated nonselective cation channel, has been found to mediate cell membrane depolarization in immune response, insulin secretion, cardiovascular diseases, and cancer." (PMID 29996905, 2018). "The prevalence of IR-A contributes to modifying the response of cancer cells to insulin and IGFs by different mechanisms." (PMID 30453495, 2018). "Atypical teratoid/rhabdoid cancer cells overexpress the IR and produce insulin, activating an autocrine IR/PI3K/Akt/mTOR loop biologically relevant for cell proliferation." (PMID 30453495, 2018). "These proinflammatory cytokines not only impair insulin action in metabolic tissues, but also favor cancer development." (PMID 30591653, 2018). "Among the three subtypes of PPARs, PPARγ modulates a broad range of physiopathological processes, including lipid metabolism, insulin sensitization, cellular differentiation, and cancer." (PMID 30012954, 2018). "More pathways were specifically dysregulated in NASH-HCCs, including those previously reported in NAFLD (calcium, insulin, hedgehog and adipocytokine signaling), and cancer (axon guidance and cell adhesion)." (PMID 30367044, 2018). "Over-expression of the enzyme prevents the inhibitory effects of accumulated saturated fatty acids on insulin signalling while abnormally high expression of the enzyme has been reported in several human cancers." (PMID 30008672, 2018). "Many antidiabetes treatments, particularly metformin, enhance insulin signaling, but this pathway can be inhibited by specific cancer treatments." (PMID 30208162, 2018). "IGF-1 and IGF-1R are known to be abundantly expressed in the PDAC tissue, and activated Insulin/IGF signaling in PDAC cells was found to regulate the basal growth rate of the cancer cells." (PMID 29475434, 2018). "Regarding the molecular basis, the postprandial blood glucose and insulin-invoked overexpression of Mucin 16 (encoding CA125) were demonstrated in animal and cancer cell models, which were mediated by the PI3K-Akt pathway." (PMID 29716620, 2018).